ZFHX3 (zinc finger homeobox 3)
Diseases named in the same sentence as ZFHX3 in open-access papers (continued):
Sharing a sentence is not in itself a finding about the gene and the disease.
non-small cell lung carcinoma (5 papers, 2017 to 2025). A group of at least three distinct histological types of lung cancer, including non-small cell squamous cell carcinoma, adenocarcinoma, and large cell carcinoma. "One previous research study proposed ZFHX3 as a tumor suppressor in non-small cell lung cancer." (PMID 28984200, 2017).
spinocerebellar ataxia type 4 (5 papers, 2024 to 2025). Spinocerebellar ataxia type 4 (SCA4) is a very rare progressive and untreatable subtype of type I autosomal dominant cerebellar ataxia (ADCA type I) characterized by ataxia with sensory neuropathy. "In five families from Skåne region in Sweden, expanded repeat expansions in ZFHX3 were identified as the cause for spinocerebellar ataxia type 4, SCA4." (PMID 38035881, 2024). "A pathogenic ZFHX3 GGC repeat expansion was recently linked to spinocerebellar ataxia type 4 (SCA4), characterized by progressive ataxia and sensory neuropathy, with all reported cases in individuals of Northern European ancestry." (PMID 40166539, 2025). "The identification of a heterozygous exonic GGC repeat expansion in ZFHX3 underlying spinocerebellar ataxia type 4 (SCA4) has solved a 25‐year diagnostic conundrum." (PMID 39635987, 2025). "The GGC repeat expansion in ZFHX3, responsible for spinocerebellar ataxia type 4 (SCA4), has only been described in individuals of Northern Europeandescent." (PMID 40459184, 2025). "ZFHX3 is located within the 16q22 locus, to which spinocerebellar ataxia type 4 (SCA4) repeatedly had been mapped; the clinical phenotype in our families corresponded well with the unique phenotype described in SCA4, and the original SCA4 kindred originated from Sweden." (PMID 38035881, 2024). "ZFHX3 is located between the markers D16S3019 and D16S512 on the long arm of chromosome 16, to which spinocerebellar ataxia type 4 (SCA4) had been mapped by conventional linkage analyses in a German and in two Swedish kindreds reported from Stockholm, Eastern Sweden." (PMID 38035881, 2024).
lung carcinoma (4 papers, 2021 to 2023). "ZFHX3, named also ATBF1, has been widely associated with the development of lung cancer when dysregulated." (PMID 34834557, 2021).
Obesity (4 papers, 2019 to 2024). Accumulation of substantial excess body fat. "Similarly, knockdown of zfh-2 in C. elegans leads to obesity in animals fed a regular diet whereas heterozygous mutation of the mouse ortholog, Zfhx3/Atbf1, leads to reduced body weight gain." (PMID 34492009, 2021). "Further emphasizing the need for future analyses of these genes, reduced expression of Zfhx3 is strongly associated with increased body fat, fat mass, and markers of metabolic syndrome including insulin sensitivity and high cholesterol in mice, suggestive of a role in obesity for this gene." (PMID 34492009, 2021). "For instance, in comparison to FTO, ZFHX3 has approximately 1 million base-pairs closer to Iroquois homeobox protein 3 (IRX3), which is known to mechanistically interact with the genetic variation of FTO to influence obesity and related metabolic disorders." (PMID 39060932, 2024). "Considering that ZFHX3 is located on chromosome 16, the same chromosome in which several SNPs in the FTO obesity-related gene are found, a possible hypothesis for the significant associations identified is that they might be in linkage disequilibrium with FTO and FTO-related genes." (PMID 39060932, 2024).
endometrial carcinoma (3 papers, 2019 to 2021). A malignant tumor arising from the epithelium that lines the cavity of the uterine body. "For example, CSMD3 and ZFHX3 are involved in ovarian cancer and endometrial carcinoma, respectively, which indicated that integration of HPV may lead to malfunctions of host oncogenes and tumor suppressors." (PMID 35058971, 2021). "For instance, by stratifying endometrial carcinoma cell lines based on mutations in both CTCF and ZFHX3, we observed a pattern of differential response to microtubule inhibitors, and this pattern would not have been apparent if we stratified cell lines based on mutations in individual genes." (PMID 31253832, 2019). "Our endometrial carcinoma analysis offered especially interesting results as it returned numerous pairs of networks with similarity, where most of the corresponding genes in these pairs - such as CTCF, NAV3, and ZFHX3 - are not typically implicated as markers of drug response." (PMID 31253832, 2019).
liver cancer (3 papers, 2016 to 2022). An epithelial or non-epithelial malignant neoplasm that arises from the liver. "For example, ZFHX3 promotes liver cancer cells’ tumor growth by interacting with HIF1A to enhance angiogenesis." (PMID 33217982, 2020). "ZFHX3, a transcription factor with many homeodomains and zinc fingers, suppresses prostatic carcinogenesis but promotes tumor growth of liver cancer cells." (PMID 33217982, 2020).
type 2 diabetes (3 papers, 2019 to 2025). "In addition, we discovered seven other potential key transcriptional regulators of gene expression networks in type 2 diabetes: Etv1, Irx1 and Foxp1 (alpha cells); Ehf, Hhex and Tcf4 (delta cells); and Zfhx3 (macrophages)." (PMID 39508880, 2025).
Atrophy (2 papers, 2025). Any weakening or degeneration, especially through lack of use. "We identified ZFHX3 GGC expansions (47–55 repeats) in 4 patients with progressive ataxia, polyneuropathy, and vermis atrophy." (PMID 40459184, 2025). "We identified ZFHX3 GGC repeat expansions (47–55 repeats) in four individuals with progressive ataxia, polyneuropathy, and vermis atrophy." (PMID 40166539, 2025).
coronary artery disease (2 papers, 2016 to 2021). "Interestingly, a recent study has shown that the CAA·TTG repeats are present along with the CAG repeats in the zinc finger homeobox 3 (ZFHX3) gene that is associated with coronary heart disease in Chinese population." (PMID 33574412, 2021).
COVID-19 (2 papers, 2023 to 2024). A disease caused by infection with severe acute respiratory syndrome coronavirus 2. "MI and CI susceptibility in patients with CDKN2B-AS1 and ZFHX3 polymorphisms, respectively, may have an effect on COVID-19 severity." (PMID 37653506, 2023). "Additionally, there was a significant association of lower LDL in severe COVID-19 patients regarding the C/T genotype of ZFHX3 (rs210626) genotype distribution and lower HDL in severe COVID-19 patients regarding the G/C and C/C genotypes of CDKN2B-AS1 (rs1333049) genotype distribution." (PMID 37653506, 2023). "In our study, we assessed the association of CDKN2B-AS1 (rs1333049) located on chromosome 9p21 and ZFHX3 (rs2106261) located on chromosome 16q22 SNPs with COVID-19 severity." (PMID 37653506, 2023). "Surprisingly, there was a significant association of a higher incidence of death in the C/T genotype in severe COVID-19 patients regarding the ZFHX3 (rs2106261) genotype distribution." (PMID 37653506, 2023). "We aimed to investigate whether there is an association between the cyclin-dependent kinase inhibitor 2B antisense RNA 1 (CDKN2B-AS1) rs1333049 and zinc finger homeobox 3 (ZFHX3) rs2106261 single nucleotide polymorphisms (SNPs) and the degree of COVID-19 severity." (PMID 37653506, 2023).
hepatocellular carcinoma (2 papers, 2022 to 2026). A malignant tumor that arises from hepatocytes. "Among these candidate genes, transcription factor Zinc Finger Homeobox 3 (ZFHX3) is known to mediate hypoxia-induced angiogenesis in hepatocellular carcinoma via transcriptional activation of VEGFA." (PMID 41543887, 2026).
Intellectual disability (2 papers, 2022 to 2024). "Loss-of-function mutations in ZFHX3 cause syndromic intellectual disability with variable phenotypes as autism spectrum disorder, facial features, relative short stature or brachydactyly." (PMID 39095619, 2024). "Heterozygous deletions at 19q12-q13.11 affecting TSHZ3, the teashirt zinc finger homeobox 3, have been associated with intellectual disability and behavioural issues, congenital anomalies of the kidney and urinary tract (CAKUT), and postnatal growth retardation in humans and mice." (PMID 36553458, 2022).
myocardial infarction (2 papers, 2011 to 2025). Gross necrosis of the myocardium, as a result of interruption of the blood supply to the area, as in coronary thrombosis. "While ZFHX3 has been implicated in the pathophysiology of obesity, SMARCA4 has been shown to regulate cholesterol levels, suggesting that the methylation of both genes could be essential biomarkers of myocardial infarction risk." (PMID 40076974, 2025).
schizophrenia (2 papers, 2008 to 2013). A major psychotic disorder characterized by abnormalities in the perception or expression of reality. "ZFHX3, RND3, KLF5, ERBB4, EGR1 and APC genes are both schizophrenia candidate genes and tumor suppression genes." (PMID 24564241, 2013).
viral infection (2 papers, 2014 to 2024). "This suggests that myeloid Zfhx3 deficiency protects against hypercapnic suppression of antiviral host defense in vivo not only by enhancing the resistance of MØs to viral infection, but also by reducing viral infection and/or replication in lung epithelial cells." (PMID 38227369, 2024). "ZFHX3 is involved in the cellular response to genotoxic and oxidative stress and its expression is known to be influenced by a large number of trans acting factors, including cytokine levels, viral infection, tissue injury and drug treatment." (PMID 25539802, 2014). "Thus, future studies should examine the role of Zfhx3 as a mediator of responses to elevated CO2 in airway and alveolar epithelial cells, as well as other cell types, in the context of viral infection." (PMID 38227369, 2024).
brain tumor (1 paper, 2021). "BM ZFHX3 mutation, CD8+ TILs, and TCR clonality level were potential factors of prognostic stratification for the surgery of oligometastatic brain tumor." (PMID 33479213, 2021).
Brugada syndrome (1 paper, 2021). A genetically heterogeneous condition characterized by complete or incomplete right bundle branch block accompanied by ST elevation in leads V1-V3. "Additionally, we identified three Zfhx3 variants in probands diagnosed with familial atrial fibrillation (p.M1260T) and Brugada Syndrome (p.V949I and p.Q2564R)." (PMID 34884836, 2021).
cardiomyopathy (1 paper, 2009). A disease of the heart muscle or myocardium proper. "ZFHX3 also interacts with MYH7 (myosin, heavy chain 7, cardiac muscle, beta, NP_000248), in which mutations are known to cause an inherited form of cardiomyopathy." (PMID 19132087, 2009).
cerebellar disorder (1 paper, 2024). Diseases that affect the structure or function of the cerebellum. "Previous work has shown that ZFHX3 plays a role in neuronal differentiation and that ZFHX3 is implied in cerebellar neurons’ responses to oxidative stress, plausibly linking variation in this gene to a cerebellar disorder." (PMID 38035881, 2024).
cerebral atherosclerosis (1 paper, 2023). Atherosclerosis of the cerebral vasculature. "The cerebral atherosclerosis-related gene PITX2, RGS7, NKX2-5, NKX2-5, and ZFHX3 are involved in AIS." (PMID 37265472, 2023).
cleft lip (1 paper, 2025). Congenital defect in the upper lip where the maxillary prominence fails to merge with the merged medial nasal prominences. "For instance, the genetic correlations of disorders such as cleft lip, craniofacial abnormalities, and microcephaly, specifically related to genes like ZFHX3 and HHAT, are consistent with previous research findings." (PMID 39928610, 2025).
dementia (1 paper, 2018). Loss of intellectual abilities interfering with an individual's social and occupational functions. "Previous research showed that genetic variants at ZFHX3 is related to dementia." (PMID 30598117, 2018).
endometrioid carcinoma (1 paper, 2021). "Furthermore, low-grade endometrioid carcinoma tiles with gland formation, low nuclear grade, and abundant tumor-infiltrating lymphocytes were present in the ZFHX3-mutated cluster, while those with much fewer lymphocytes were in the wild-type cluster." (PMID 34622237, 2021).
fecal incontinence (1 paper, 2024). Involuntary passage of stool from the rectum. "Furthermore, ZFHX3 was identified as one of a few candidate genes for sporadic Hirschsprung disease, which might connect ZFHX3 to the pathology observed in the enteric nervous system and the clinical symptoms of diarrhea and fecal incontinence." (PMID 38035881, 2024).
hypospadias (1 paper, 2025). Hypospadias is the displacement of the urethral meatus on the ventrum of the penis. "It is reported that SNP loci located in other homologous gene box families (such as HOXA cluster, IRX3, IRX5, ZFHX3, etc.)also increase the risk of hypospadias, which may suggest the focus of the future research." (PMID 40547448, 2025).
Left atrial enlargement (1 paper, 2017). Increase in size of the left atrium. "Therefore, we hypothesized that PITX2, KCNN3 and ZFHX3 associate with left atrial enlargement and persistent AF and subsequently with ablation outcome." (PMID 28381281, 2017).
metastatic tumors (1 paper, 2023). "Single nucleotide variant (SNV) frequencies of 34 candidate genes (including KMT2D (46.4%), ZFHX3 (33.3%), JAK1 (31.9%), and RNF43 (27.5%)) and 16 candidate genes (including KMT2D (33.3%) and JAK1 (28.3%)) were higher in MMR-d primary tumors and MMR-d metastatic tumors, respectively." (PMID 36675550, 2023).
multicystic dysplastic kidney (1 paper, 2024). Multicystic dysplastic kidney (MCDK) is a congenital anomaly of the kidney and urinary tract (CAKUT) in which one or both kidneys (unilateral or bilateral MCDK respectively) are large, distended by multiple cysts, and non-functional. "In whole-exome sequencing data of two siblings with genetically unresolved multicystic dysplastic kidneys (MCDK), prioritizing variants in murine CAKUT-associated genes yielded a rare variant in the teashirt zinc finger homeobox 3 (TSHZ3) gene." (PMID 39420202, 2024).
myeloma (1 paper, 2025). "Recurrent lymphoid CH mutations (in FAT1, KMT2D, MGA, and SYNE1) and myeloma driver gene mutations (in ZFHX3 and DIS3) were found in the dominant clonal and subclonal plasma cell populations." (PMID 40152254, 2025). "Despite the distinct burden of subclonal mutations, some CH mutations were conservative among MM, AL, POEMS, and MGUS, including lymphoid and myeloid CH mutations, such as those in KMT2D, FAT1, MGA, and SYNE1, and myeloma driver genes like ZFHX3 and DIS3." (PMID 40152254, 2025).
Nystagmus (1 paper, 2024). Rhythmic, involuntary oscillations of one or both eyes related to abnormality in fixation, conjugate gaze, or vestibular mechanisms. "Slow horizontal saccades were seen in all individuals with ZFHX3 repeat expansions, there was no nystagmus, and smooth pursuit eye movements were frequently unimpaired." (PMID 38035881, 2024).
orofacial cleft (1 paper, 2025). A disorder of facial skeleton that is characterized by cleft lip and/or cleft palate that result in feeding, speech and hearing problems caused by failures during development. "In gene ZFHX3, rs55989215 in inferior facial angle A (p = 1.00 x 10−7) and inferior facial angle B (p = 1.27x 10−7) has been associated to orofacial cleft and facial morphology dysmorphia." (PMID 39928610, 2025).
Parkinsonism (1 paper, 2025). Characteristic neurologic anomaly resulting from degeneration of dopamine-generating cells in the substantia nigra, a region of the midbrain, characterized clinically by shaking, rigidity, slowness of movement and difficulty with walking and gait. "In summary, this study confirms the presence of a ZFHX3 GGC repeat expansion in Latin America, documents repeat instability and founder haplotype conservation, and broadens the clinical spectrum of SCA4 to include parkinsonism." (PMID 40459184, 2025).
paroxysmal AF (1 paper, 2018). "We genotyped ZFHX3 SNP rs2106261 and compared the minor (T) allele frequency between 362 paroxysmal AF (PAF) patients underwent pulmonary vein isolation (PVI) and 627 non-AF controls." (PMID 30180182, 2018). "If the paroxysmal AF patients possess the ZFHX3 SNP minor allele, we can preprocedurely select only PVI as AF ablation strategy." (PMID 30180182, 2018). "Given that ZFHX3 SNP acts through PITX2c expression levels, AF trigger in paroxysmal AF patients with ZFHX3 SNP minor allele was related to PV and they easily cured by PVI." (PMID 30180182, 2018). "We performed PV isolation and paroxysmal AF patients with ZFHX3 SNP minor allele have lower AF recurrence rate than those without." (PMID 30180182, 2018).
partial epilepsy (1 paper, 2024). "In addition, compound heterozygous ZFHX3 variants were identified in children with partial epilepsy." (PMID 39095619, 2024).
teratoma (1 paper, 2022). A non-seminomatous germ cell tumor characterized by the presence of various tissues which correspond to the different germinal layers (endoderm, mesoderm, and ectoderm). "In our study, CARD11(caspase recruitment domain family member 11) (mutated in 18% intracranial teratomas), IRS1(insulin receptor substrate 1) (18%), PSMD11(16%), RELN(16%), RRAS2(16%), SMC1A(16%), SYNE1(16%) and ZFHX3(16%) were the tumor-related genes with the highest mutation rates in our cohort." (PMID 36457486, 2022).